MIR3192 (microRNA 3192)
Synonyms: hsa-mir-3192; mir-3192
Gene: MicroRNA gene on chromosome 20 (18,470,615 to 18,470,691, forward strand). Ensembl gene ENSG00000265137.
Homologues: Orthologues: chimpanzee MIR3192 (100% identical).